INS (insulin)
Diseases named in the same sentence as INS in open-access papers (continued):
Sharing a sentence is not in itself a finding about the gene and the disease.
schizophrenia (continued). "Patients with severe mental health disorders such as schizophrenia are usually too disorganized to manage their own insulin regimen which requires multiple daily doses, correction of blood sugar for meals and a different, longer acting insulin to be administered once before bedtime." (PMID 38090176, 2023). "Indeed, the placenta&brain schizophrenia TWAS genes imply an activation of insulin signaling in placenta and its inhibition in prenatal cortical brain, due to the presence of genes with opposite sign of association in the two organs." (PMID 37188697, 2023). "Insulin as an important neuromodulator could affect neurotransmitters to regulate schizophrenia symptoms and change cerebello-cortical connectivity pattern." (PMID 36676092, 2023). "For example, dysregulations of insulin, cortisol, glucagon, glucagon-like peptide 1, cholecystokinin, adiponectin, ghrelin, leptin, orexin, prolactin, and oxytocin have been observed during treatment with antipsychotics among persons with schizophrenia." (PMID 35806096, 2022). "We examined 195 patients with schizophrenia (90 with and 105 without MetS) for the association of serum levels of ghrelin, insulin, and leptin with metabolic abnormalities." (PMID 36294794, 2022). "In schizophrenia (SZ), Down Syndrome, and bipolar disorder (BD), increased brain insulin resistance and reduced IGF-1 signaling drive allostatic load/overload, leading to physiological dysregulation and the presentation of more severe symptoms throughout the body." (PMID 36429060, 2022). "InSakel’s first published paper on insulin treatment for schizophrenia, heclaimed that 88 per cent of his first group of over 100 patients with arecent onset of schizophrenia showed a good degree of improvement followinginsulin coma therapy, with 70 per cent making a full recovery." (PMID 34935541, 2022). "Previous studies have suggested that the glucose signalling cascade in the brain is impacted in schizophrenia, where excess insulin may serve as a compensatory mechanism to maintain glycaemic control." (PMID 36310155, 2022). "Additionally, radiotracer or detection methods are expected to clarify the central insulin action in patients with schizophrenia." (PMID 34108878, 2021). "Given the central importance of dopaminergic dysregulation, cognitive deficits, and metabolic dysfunction in schizophrenia, the potential role of central nervous system insulin signalling in the pathophysiology of schizophrenia is an interesting field to be explored." (PMID 32528326, 2020). "Notably, studies of multiple-episode schizophrenia patients revealed increased levels of leptin and insulin." (PMID 32547431, 2020). "Best-fit general linear models of insulin resistance within persons with schizophrenia (N = 145)." (PMID 31065243, 2019). "Cytokines that are important in glucose utilization and insulin sensitivity appear to be elevated and might be involved in pathogenesis of schizophrenia." (PMID 29163240, 2017). "Data Sources: MEDLINE, Google Scholar, Cochrane Database and PsycINFO databases were searched for articles containing all the following exploded MESH terms: schizophrenia [AND] antipsychotic agents/neuroleptics [AND] (weight gain [OR] lipids [OR] insulin [OR] leptin) [AND] treatment outcome." (PMID 29403343, 2017). "Abnormalities in brain insulin signaling and reduced brain expression of insulin receptors are reported in schizophrenia, and antipsychotics may also impact these pathways." (PMID 29403343, 2017). "Recent molecular studies have indicated that there are abnormalities in the glucose metabolism and insulin signaling pathways in subgroups of unmedicated people with schizophrenia indicating a shared genetic vulnerability between type-2 diabetes and schizophrenia in some cases." (PMID 25309466, 2014). "Our finding of higher prolactin/growth hormone and insulin/growth hormone ratios in female first onset schizophrenia patients suggests that this effect could also be sex-specific." (PMID 24244349, 2013).
schizophrenia (continued). "Taken together, these findings suggest that female schizophrenia patients may show signs of better insulin signalling, which may afford some protection against development of more severe psychiatric symptoms and disease associated deficits." (PMID 24244349, 2013). "In agreement with this, schizophrenia patients in the present study were insulin resistant." (PMID 22257447, 2012). "A similar condition may occur in the brains of schizophrenia patients due to impaired glial glucose uptake as a consequence of insulin resistance." (PMID 20631894, 2010). "It showed strong positive loadings for RVIs of schizophrenia, BD, T2D and PD, reflecting a shared neuroanatomical signature across psychiatric and somatic conditions, likely rooted in overlapping mechanisms such as oxidative stress, neuroinflammation and insulin resistence." (PMID 41160917, 2025). "These genes include genes involved in both cognitive function and glucose metabolism that previous studies have suggested may increase the risk of T2DM in schizophrenia patients and vice versa, including the AKT signaling pathway, which plays a key role in insulin metabolism in the liver." (PMID 37515308, 2023). "Therefore, we speculated that the possible explanations for the association between the plasma COLA and homocysteine levels might be related to the impaired glucose–insulin homeostasis in the OLA-treated patients with schizophrenia." (PMID 35800023, 2022). "Although it is still debatable whether this is a compensatory mechanism for insulin resistance or a direct consequence of β-cell stimulation by antipsychotics, increased basal insulin secretion at high concentrations was observed in persons with schizophrenia after receiving antipsychotics." (PMID 35806096, 2022). "Since the deleterious effect of olanzapine on insulin secretion was reverted by the co-treatment with an ER stress inhibitor, individuals with schizophrenia receiving treatment with this SGA could follow a combinatorial therapy aimed to reduce ER stress-induced beta cell dysfunction." (PMID 35629947, 2022). "Thus, cerebral insulin resistance in schizophrenia may induce reduced signal transduction for gamma-aminobutyric acid (GABA), N-methyl-d-aspartic acid (NMDA), dopamine-D2 receptors, and reduced levels of brain-derived neurotrophic factor (BDNF)." (PMID 32121669, 2020). "Thus, altered insulin resistance may be part of a whole-body syndrome that manifests in the behavioral disorder of schizophrenia." (PMID 31065243, 2019). "Thus, it is plausible that central dopamine receptor blockade by antipsychotics in schizophrenia may produce both peripheral insulin resistance and poor cognition." (PMID 30568606, 2018). "In the context of these findings, combined with the historical observation that insulin-induced comas can ameliorate psychotic symptoms, it is appealing to speculate that central insulin signaling on dopamine neurons may play a role in the pathology and treatment of schizophrenia." (PMID 25716779, 2015). "The interacting pathways involving biological function may also contribute to the pathology of schizophrenia which includes transcription activity, signaling pathway, cancer-related pathway, tumor suppression, coagulation, insulin secretion, cell cycle, cell differentiation and apoptosis." (PMID 25522158, 2014). "Literature-based analysis suggests that miR-9 exerts predominantly inhibitory effects on schizophrenia-related genes (e.g., IL1B, ABCB1, FGFR1) while promoting the expression of INS, indicating a potential protective role of miR-9 against schizophrenia." (PMID 40779062, 2026). "A proteomic analysis found that insulin and leptin in the plasma of patients with MDD or schizophrenia increase, illustrating that MDD patients already have metabolic abnormalities before medical treatment." (PMID 40123458, 2025).
schizophrenia (continued). "Pathways analysis on the 203 placental-specific schizophrenia TWAS genes supported the enrichment for mTOR signaling, insulin, estrogen, and EIF2 signaling." (PMID 37188697, 2023). "Inversely, the PRSs of some psychiatric disorders, such as schizophrenia (SCZ), autism spectrum disorder, cannabis disorder, insulin‐related traits, and atopic dermatitis, were positively correlated with longevity." (PMID 35754110, 2022). "However, there is growing evidence that elevated circulating insulin and insulin-related peptides and abnormal insulin response to glucose can be identified already in drug-naïve first-episode patients, suggesting that insulin signaling is impaired in schizophrenia." (PMID 22257447, 2012). "This left 164, 164, 163, 153, 117, 80, 150, 150, 178, 178, and 93 SNPs as IVs for MR analyses of schizophrenia on HDL, LDL, triglycerides, total cholesterol, BMI, WHR, systolic blood pressure, diastolic blood pressure, fasting glucose, fasting insulin and HbA1c, respectively." (PMID 37091807, 2023). "Like earlier critics, he highlighted how manystudies of insulin therapy involved small numbers of patients, had no propercomparator group, were not blinded, and that there were no standardizeddefinitions of schizophrenia itself or of recovery." (PMID 34935541, 2022). "Nevertheless, they proposed that chlorpromazine should bethe ‘treatment of choice’ for people with schizophrenia, and insulin shouldbe reserved for people in whom this did not work." (PMID 34935541, 2022). "Our group level results suggest that cholesterol, triglyceride, and insulin levels do not differ in children and adolescents with later development of schizophrenia, any non-affective psychosis or affective disorder compared to controls." (PMID 36220836, 2022). "Clinical use of insulin as non-glycemia management therapy administered intravenously was firstly described for morphine addiction treatment, schizophrenia symptom mitigation, and dementia praecox." (PMID 33799976, 2021). "The use of insulin as non-glycemia management therapy dates back to the 1930s, when Manyfreed Sakel used it, with intravenous administration, to treat morphine addiction and schizophrenia." (PMID 33799976, 2021). "Therefore, altered S100B protein expression in schizophrenia probably indicates systemic disturbances in cellular energy supply (e.g., by disrupted peripheral and cerebral insulin signaling) rather than adipocyte- or glia-specific pathologies." (PMID 20631894, 2010). "Our aim was to study whether insulin and lipid trajectories differ from controls in children and adolescents who later develop schizophrenia, or any non-affective psychotic disorder defined by Diagnostic and Statistical Manual of Mental Disorders, 4th edition (DSM-IV)." (PMID 36220836, 2022). "DMO might have a counteracting effects on glucose-insulin homeostasis and lipid metabolic abnormalities, which suggests that regular measure of various metabolic parameters and drug monitoring on both OLA and DMO are recommended in OLA-treated patients with schizophrenia." (PMID 35800023, 2022). "Interestingly, reduced glucose tolerance and impaired insulin sensitivity have been reported in schizophrenia patients and their siblings, relative to healthy subjects, which suggests that metabolic dysfunction in schizophrenia is not exclusive to the brain." (PMID 29616444, 2019). "Entitled simply ‘The insulin myth’, the paper showed there to be no basis for the belief that the radical treatment, involving putting patients into a deep coma for up to 15 mins five or six mornings a week for as much as 10 weeks, had a beneficial effect in the treatment of schizophrenia." (PMID 25237504, 2014).
colon carcinoma (129 papers, 2005 to 2025). "The biological mechanisms underlying how physical activity reduces colon cancer risk have mainly been attributed to decreased adiposity and associated reductions in circulating insulin and proinflammatory cytokines." (PMID 35213038, 2022). "This study aimed to elucidate the underlying mechanism by which metformin reverts insulin‐induced oxaliplatin resistance in human colon cancer HCT116 cells." (PMID 32248666, 2020). "The results of our study show that insulin pretreated colon cancer cells are significantly more susceptible to commonly used chemotherapeutics: FU, IRI, OXA, DOC." (PMID 31719636, 2019). "The results of our study show that insulin-pretreated colon cancer cells are significantly more susceptible to commonly used chemotherapeutics." (PMID 31719636, 2019). "The MTT viability assay showed that colon cancer cells sensitized by insulin are more susceptible to chemotherapeutic drugs." (PMID 31719636, 2019). "The study aimed to elucidate the effects of insulin, an inexpensive drug with a convincing safety profile, on the susceptibility of colon cancer to commonly used chemotherapeutic agents." (PMID 31719636, 2019). "A lot of studies have observed increased levels of insulin have been related with an increased risk of colon cancer." (PMID 29793481, 2018). "The aim of this study was to investigate the effect of insulin on the proliferation and migration of colon cancer cells and its underlying mechanism." (PMID 29793481, 2018). "Metformin and insulin differently affect the risk of colon cancer in type 2 diabetic patients, however their effects on colon adenoma is not clear." (PMID 29383018, 2018). "Our overall results are consistent with previous findings of high insulin or C-peptide concentration on elevated risk for colorectal or colon cancer." (PMID 30740588, 2018). "Insulin, an important growth factor acting as a cell mitogen, when at high concentrations increase the risk of colon cancer by promoting growth of tumors." (PMID 26901856, 2016). "Eating red meat raises colon cancer risk, possibly by stimulating endogenous insulin secretion, or by producing carcinogens." (PMID 26980842, 2016). "What’s more, glargine insulin treatment was believed to increase the risk of developing colon cancer." (PMID 26901856, 2016). "TC:0000227 included words such as “insulin”, which is known to be associated with colon cancer risk and important for mediating tumor growth." (PMID 26588252, 2015). "Breast, ovarian, prostate, lung, and colon cancer are the tumor tissues where the insulin/IGF system has been directly linked to tumor development and progression." (PMID 26528439, 2015). "Even a reduction in cardiovascular disease and the risk for colonic cancer as well as boosting cognitive function were demonstrated most likely due to an improvement in insulin sensitivity." (PMID 24643026, 2014). "Serum insulin and its more stable surrogate biomarker, C-peptide, are significant risk factors for colon cancer in both men and women." (PMID 23056418, 2012). "It is hypothesized that the increase in crypt foci and colon cancer risk through insulin activity may be related to the induction of G9a, resulting in methylation-mediated degradation of FOXO1." (PMID 36830954, 2023). "High glycemic index diets, which chronically raise post-prandial blood glucose, may at least in part increase colon cancer risk via the insulin/insulin-like growth factor 1 (IGF-1) signaling pathway." (PMID 34208601, 2021). "The study aimed to elucidate the effects of insulin (INS), an inexpensive drug with a convincing safety profile, on the susceptibility of colon cancer to chemotherapeutic agents: 5-fluorouracil (FU), oxaliplatin (OXA), irinotecan (IRI), cyclophosphamide (CPA) and docetaxel (DOC)." (PMID 31719636, 2019). "Moreover, it has been demonstrated that the increased blood levels of insulin in type II diabetes individuals, caused by insulin-resistance, enhance the risk to develop colon cancer." (PMID 26528439, 2015).
colon carcinoma (continued). "Elevated blood glucose and insulin levels may increase the risk of colon cancer." (PMID 37513568, 2023). "As other recognized pathways in the black module regulate gene expression in pancreatic beta cells and the synthesis/secretion of Incretin, there may be an association between insulin secretion, colon cancer, and genes in this module which needs to be further studied." (PMID 35194111, 2022). "Some indirect evidence that exercise might preserve cardiovascular status in cancer patients comes from a prospective study in colon cancer survivors reporting that physical exercise caused lower insulin levels and insulin resistance, compared to standard of care." (PMID 34049593, 2021). "And the insulin treatment may further elevate risk for colon cancer in patients with T2DM." (PMID 26901856, 2016). "Thus, in principle, healthy diet and lifestyle behaviors could potentially lower insulin levels thereby reducing risk of colon cancer." (PMID 22216097, 2011). "Insulin promotes PD-L1 production and transport in colon cancer stem cells via PI3K/Akt/mTOR signalling." (PMID 39075562, 2024). "Several risk factors including hormones like insulin and insulin like growth factors (e.g., IGF-1) have been considered responsible for growth and progression of colon cancer." (PMID 37560308, 2023). "Our study shows that insulin promotes colon tumor growth, decreases the number of tumoral infiltrated CD8+ T cells, and weakens the therapeutic effect of anti-PD1 on colon tumor growth inhibition." (PMID 36033393, 2022). "Finally, higher fasting insulin was associated with an elevated risk of endometrial cancer (OR = 3.71, 95% CI 2.06–6.67) and using an exposure instrument generated from sex-combined data, higher plasma adiponectin was associated with diminished colon cancer risk (OR = 0.50, 95% CI 0.31–0.81)." (PMID 36558416, 2022). "Taken together, insulin and OA promoted colon carcinoma cell colonization and outgrowth in the progress of CRC occurrence and development and performed a synergistic oncogenic effect in vivo." (PMID 34434893, 2021). "The metabolic stress response was also evaluated in terms of altered secretion of hormones, such as cortisol and insulin, in colon cancer patients undergoing EA or IA surgeries." (PMID 33958669, 2021). "We are not aware of any previous studies comparing mRNA expression of parameters of the insulin/IGF system in different Dukes’ stages of colon cancer." (PMID 34290976, 2021). "There are only a few experimental studies which have investigated effects of glucose alone, and glucose in combination with insulin/insulin-like growth factors (IGF) on the growth of colon cancer." (PMID 34290976, 2021). "Stimulatory effects of insulin and IGFs on cell growth were observed only in colon cancer cells originating from Dukes’ stage C and D. IGF-II stimulated migration in Dukes’ stage B cells only." (PMID 34290976, 2021). "A nonlinear ANN was employed in this study to uncover important aspects of biological cue-signal-response systems using TNF-, EGF-, and insulin-mediated response of HT-29 human colon carcinoma cells." (PMID 32314080, 2020). "After our observations of in vitro effects, insulin and FU were evaluated in a mouse allograft model of colon cancer." (PMID 31719636, 2019). "We observed a dose-dependent increase of PD-L1 protein expression, suggesting that insulin can generally stimulate PD-L1 production in colon cancer cells." (PMID 30770752, 2019). "To examine the effects of insulin on cell viability and apoptosis, we performed an in vitro analysis on colon cancer cell lines Caco-2 and SW480." (PMID 31719636, 2019). "CCK8 assay and transwell assay were used to investigate the effect of different concentrations of insulin and ACAT1siRNA on human colon cancer cell line HT-29." (PMID 29793481, 2018).